TNF (tumor necrosis factor)
Diseases named in the same sentence as TNF in open-access papers (continued):
Sharing a sentence is not in itself a finding about the gene and the disease.
silicosis (continued). "The interaction between IL-1RA +2018 and TNF-α-238 showed a strong independent association between each SNP and silicosis, which may be attributed to the overlapping functions of inflammatory cytokines." (PMID 40182855, 2025). "TNF a classical pro-inflammatory cytokine, stimulates fibroblasts proliferation and interacts with other inflammatory mediators, such as IL-1β, IL-6, and IL-8, to modulate immune responses and inflammatory reactions which are associated with silicosis." (PMID 40470053, 2025). "TNF-α-308 G/A and−238A/G polymorphisms may be correlated with silicosis susceptibility, especially in Asians." (PMID 39866352, 2024). "Most studies show that some high-risk factors (HIV, organ transplantation, silicosis, treatment with tumor necrosis factor-α (TNF-α) blockers, hemodialysis, and close contact with Mtb excreting patients) accelerate the reactivation of TB infection significantly." (PMID 35324595, 2022). "Also, SiO2 induced macrophage senescence and silicosis in lung tissue, both of which were accompanied by increased fibrosis-associated factors (IL-1β, IL-6, TNF, and TGF-β1) and MMPs (MMP2, MMP9 and MMP12)." (PMID 35959439, 2022). "Inter-individual differences in IL-1 and TNF-α production sustain the idea that silicosis and the progression to its complicated form are linked to the host’s genetic predisposition to produce these proteins, since in inflammatory diseases, some allelic variants were found to be overexpressed." (PMID 36672608, 2022). "First, genotyping of the TNF polymorphisms should be taken into account in all studies referring to TNF as a biomarker for silicosis, as TNF was shown to determinate the susceptibility to silicosis, and of developing a complicated form (progressive massive fibrosis)." (PMID 36672608, 2022). "Our findings show that also other TNF polymorphisms are linked to silicosis." (PMID 36672608, 2022). "Furthermore, this is the first study to confirm the association between the TNF −238A/G polymorphism and silicosis susceptibility." (PMID 30643011, 2019). "The present meta-analysis found a significant association between TNF −308A polymorphism and silicosis in the overall population, and a significant association of AA+AG genotype of TNF −308A/G polymorphism with susceptibility to silicosis was noted." (PMID 30643011, 2019). "The present meta-analysis showed that TNF −308A/G polymorphism was related to silicosis in Asians." (PMID 30643011, 2019). "Similarly, there was significant association between TNF −238A allele and all silicosis cases, and AA+AG genotype of TNF −238A/G polymorphism indicated a significant association with silicosis." (PMID 30643011, 2019). "Thus, it seems necessary to perform a meta-analysis that includes the most updated data to investigate the relationship between TNF gene polymorphisms and the risk of silicosis." (PMID 30643011, 2019). "High-risk factors (HIV/AIDs, transplantation, silicosis, TNF-α blockers, close contacts, kidney dialysis) contribute to a significantly increased TB reactivation rate, and for countries with a low TB prevalence, patients with high-risk factors should undergo screening and treatment for LTBI." (PMID 26839146, 2016). "However, according to the power analysis, our study had greater than 80% to detect the effects of TNF-α polymorphism on silicosis, assuming an OR of 1.45." (PMID 24124578, 2013). "In the current study, a meta-analysis of nine individual studies was conducted to determine whether there was a relationship between TNF-α-308G/A polymorphism and silicosis risks in the whole population." (PMID 24124578, 2013). "Finally, a total of nine published articles including 1267 cases and 1214 controls reported the relationship between TNF-α-308G/A gene polymorphism and the susceptibility to silicosis." (PMID 24124578, 2013). "TNF-α-308 G/A polymorphism might lead to an increased risk of silicosis susceptibility, especially for Asians." (PMID 24124578, 2013).
silicosis (continued). "Previously, TNFα has been implicated as a central mediator in the pathogenesis of silicosis." (PMID 19479048, 2009). "Thereby, the current study indicates TNF-α-308G allele might increase silicosis risk." (PMID 24124578, 2013). "Overexpression of TNF-α result in the progression of the disease, making it a viable detection biomarker for the early-stage silicosis patients." (PMID 40470053, 2025). "Our previous study suggested that blocking exosome secretion alleviated lung inflammation and decreased the expression of IL-1β, IL-6 and TNF-α in bronchoalveolar lavage fluid in mice with silicosis." (PMID 38454505, 2024). "Tumor necrosis factor–α (TNF–α) and interleukins (ILs) are the first to be discovered as contributors in silicosis progression and potential biomarkers of silicosis diagnostics." (PMID 39882130, 2024). "TNF-α exerts an important influence on the pathogenesis of silicosis through NF-κB, which mediates the occurrence of apoptosis and inflammation." (PMID 39866352, 2024). "Silicosis can be prevented with the administration of an anti-TNF antibody but is aggravated by exogenous recombinant TNF-α application." (PMID 38515835, 2024). "That TNF-α plays an important role in the development of silicosis has been demonstrated in SiO2-treated rats." (PMID 38515835, 2024). "Protein levels of IL-1β, IL-6, and TNF-α increased in the lungs of rats with silicosis and significantly decreased in YCF- and TET-treated rats." (PMID 37381044, 2023). "Compared with CG group, the secretions of serum TGF-β1, CTGF, TNF-α and IL-6 were significantly increased in the silicosis group." (PMID 35379204, 2022). "The secretions of TGF-β1, CTGF, IL-6 and TNF-α in silicosis group were significantly higher than that in control group (p < 0.05)." (PMID 35379204, 2022). "Experimental animal studies and clinical trials show that TNF-α and IL-1 are important in the regulation of fibrotic mediators in silicosis." (PMID 36672608, 2022). "The TNF-α over IL-10 ratio was evaluated, and the results showed a ratio less than 1 had a protective effect for developing silicosis." (PMID 36672608, 2022). "Based on KEGG pathway analyses of target proteins, both TNF and Toll-like receptor signaling pathways were related to senescence responses and silicosis." (PMID 35959439, 2022). "TNF-α holds several important roles in silicosis, including triggering the influx of inflammatory cells and release of other cytokines." (PMID 36672608, 2022). "Silica-stimulated macrophages activate pattern recognition receptors (PRRs) and NLRP3 inflammasome and release IL-1β, TNF-α, and interferons, which are the key mediators of silicosis pathogenesis." (PMID 36341426, 2022). "Previous research demonstrated that T-helper (Th) 1 type inflammation exists in the early stage of silicosis, which is characterized by increased levels of tumor necrosis factor alpha (TNF-α) and interferon gamma (IFN-γ)." (PMID 34149803, 2021). "Fas and TNF-α expression in AMs from silicosis patients were significantly higher than those from healthy volunteers or observed objects." (PMID 34360876, 2021). "It has been recognized that silica-activated AMs release many cytokines, like TNF-α, interleukin-1β (IL-1β), and IL-6, etc., which is the basis of silicosis fibrosis." (PMID 34360876, 2021). "In AMs from observers and silicosis patients, we found that the concentrations of IL-1β, IL-6, and TNF-α were significantly higher in the presence of LPS than those in the absence of LPS (P < 0.01)." (PMID 33817248, 2020). "In this regard, tumor necrosis factor (TNF)-α derived from alveolar macrophages in the lung is important in regulating these mediators in silicosis." (PMID 30643011, 2019). "The increased expression of TNF-α during silicosis leads to fibroblasts recruitment and proliferation." (PMID 27066079, 2016). "Tumor Necrosis Factor α (TNF-α), which promotes the activation of innate immune cells, is also implicated in the pathogenesis of silicosis." (PMID 25050810, 2014).
silicosis (continued). "In humans, several investigators have stressed the close link between innate immune cytokines (IL-1 and TNF-α), chronic inflammation and silicosis." (PMID 25050810, 2014). "In many studies, serum TNF-α level in the silicosis groups are significantly higher than that in the control groups." (PMID 24124578, 2013). "Current evidence from experimental and clinical studies proves that the pathologic process of silicosis is promoted by the increased secretion of some proinflammatory cytokines such as tumor necrosis factor-alpha (TNF-α)." (PMID 24124578, 2013). "TNF-α is one of the most relevant cytokines to the biological events in silicosis such as inflammation and fibrosis." (PMID 24124578, 2013). "Studies are available related to oxidative stress, ROS, RNS, TNF and NF-kβ, but this area is less approached by the scientists so far in caspase activation in silicosis." (PMID 21120077, 2010). "The acute inflammatory cytokines Interleukin-1 beta (IL-1β) and Tumor Necrosis Factor alpha (TNFα) are prime examples and potent inducers of NF-κB themselves, and are known to be involved in silicosis." (PMID 20492675, 2010). "TNFα and IL-1β are considered important factors in the development of silicosis and are well-known inducers of NF-κB in various cell types." (PMID 20492675, 2010). "Centrally located in the TNFα signal pathway, NF-κB activation mediates the inflammatory and cell survival effects of TNFα and therefore constitutes a logical target for antagonism in silicosis." (PMID 19479048, 2009). "Further cell-cell communication analysis revealed that in silicosis, immune cells persistently release cytokines such as TNF and IFN-γ, which act on the C0 and C2 subpopulations through related signaling pathways, causing sustained damage, inducing specific apoptosis, and inhibiting angiogenesis." (PMID 40969743, 2025). "Moreover, in silicosis, TNF-α stimulation promotes the secretion of other cytokines, influences the function of signaling pathways, and potentiates the proliferation of fibroblasts and the deposition of collagen." (PMID 38515835, 2024). "Moreover, the expression of silicosis related cytokines (IL-1β, IL-6, TNF-α, and TGF-β1) in BALF was further detected using ELISA." (PMID 39060930, 2024). "The marked increases in TNF-α and ILs could be observed in silicosis patients before the onset of clinical signs and radiographic changes, making them promising biomarkers for early diagnosis of silicosis." (PMID 39882130, 2024). "Patients with silicosis seem to have a chronic inflammatory process that is consistent with the augmented levels of some pro-inflammatory cytokines, i.e., IL-1β, IL-6, IL-7, IL-8, IL-16, IL-17A, IL-33 and TNF-α were observed in this work." (PMID 36675056, 2023). "In human plasma/serum, TNF-α levels in patients with silicosis or IL-1β, IL-6 and TNF-α in CWP patients have also been reported to be increased compared to control groups and even between simple pneumoconiosis and PMF groups, in accordance with the results in the present study." (PMID 36675056, 2023). "In a recent clinical study, a group of silicosis patients was divided into two categories to evaluate a potential treatment for silicosis (acetylcysteine + tetrandrine) and its effect on serum IL-6 and TNF-α levels." (PMID 36672608, 2022). "As inflammatory cytokines IL-6, IL-1β, TNF-α are also potent inducers of GM-CSF, it is not surprising that these cytokines are strongly associated with each other and act as predictors for silicosis patients." (PMID 36311760, 2022). "Similarly, our study found that the secretion of serum TGF-β1, CTGF, TNF-α and IL-6 were higher in patients with silicosis than in healthy subjects." (PMID 35379204, 2022). "In this study, serum levels of S100A4, transforming growth factor-β1 (TGF-β1), connective tissue growth factor (CTGF), interleukin-6 (IL-6) and tumour necrosis factor-α (TNF-α) in patients with silicosis (n = 42) and control group (CG, n = 12) were measured by ELISA." (PMID 35379204, 2022).
silicosis (continued). "If TNF-α/IL-10 ratio is supraunitary, IL-10 is not able to suppress the pro-inflammatory effect of TNF-α, suggesting that the risk factor for silicosis should be derived from this ratio and not from the independent values of TNF-α and IL-10." (PMID 36672608, 2022). "In silicosis, IL-10 is elevated but has a dual effect: on one side, IL-10 limits the amplitude of the inflammatory response by suppression of the production IL-1β, IL-6 and TNF-α in monocytes and macrophages." (PMID 36672608, 2022). "Based on these results, the authors concluded that peripheral blood IL-6 and TNF-α levels are important for silicosis management, and their detection could reduce the number of X-rays as a follow-up procedure." (PMID 36672608, 2022). "Furthermore, treatment with anti-FasL Antibodies inhibited the release of TNF-α in the AMs of a silicosis mice model." (PMID 34360876, 2021). "TNF-α has been recognized as a biomarker for the early diagnosis of silicosis." (PMID 34360876, 2021). "Macrophages play a crucial role in the pathophysiology of silicosis by secreting pro-inflammatory mediators, such as IL-1β, TNF-α, IL-6, MIP-1, and MIP-2, as well as growth factors and fibrogenic mediators, which lead to fibroblast activation and collagen deposition." (PMID 29126438, 2017). "Previous studies have found that some high-risk factors (including human immunodeficiency virus (HIV), organ transplantation, silicosis, tumor necrosis factor-alpha blockers, close contacts and kidney dialysis) contribute to a significantly increased TB reactivation rate." (PMID 26839146, 2016). "Previous studies have shown that the incidence of silicosis may be influenced by genetic factors such as IL-4, IL-1, and tumor necrosis factor (TNF)-α." (PMID 26496436, 2015). "Tumor necrosis factor alpha (TNFα) plays a central role in the pathogenesis of silicosis." (PMID 19479048, 2009). "TNFα expression and NF-κB activation was determined by performing immune staining in paraffin embedded sections of lung tissues isolated from the lungs of subjects afflicted with silicosis at the time of lung transplantation." (PMID 19479048, 2009). "In humans, compelling evidence indicates that polymorphism of the TNFα gene promoter (TNF-308: denominated TNF-A allele 2) is associated with silicosis disease severity, although not with disease frequency, in South African miners." (PMID 19479048, 2009). "Currently, there is no documented link between TNF polymorphism-related susceptibility to infections and silicosis, but it remains open whether a direct association is possible, given the susceptibility of patients with silicosis to pulmonary tuberculosis." (PMID 36672608, 2022). "Dominant model of TNF −238A/G polymorphisms (AA+AG vs. GG) showed significantly increased silicosis risk for Caucasian population, but it might not be reliable because only one published article in Caucasian population was included." (PMID 30643011, 2019). "AM apoptosis also contributes to the pathogenesis of TB and silicosis, with increased expression of cellular apoptosis receptors (FAS) and their ligands (FASLG and TNFα), promoting the recruitment of inflammatory cells." (PMID 40531729, 2025). "Several conditions increase the risk of TB, including malnutrition, alcohol abuse, smoking, anemia, diabetes, anti-TNF drugs, HIV infection, and silicosis." (PMID 40531729, 2025). "In conclusion, we identified TNF, MMP9, NF-κB1 and TLR2, that contribute to the therapeutic effects of PFD in silicosis." (PMID 40470053, 2025). "Subsequently, these macrophages undergo dysregulated polarization, with secretion of abundant cytokines such as IL-1β, IL-6, TNF-α, and TGF-β1, further promoting inflammation and progression of silicosis." (PMID 39060930, 2024). "Several candidate biomarkers for silicosis have been identified, namely, the interleukins, TGF-β, TNF-α, GF, chemokines, inflammatory proteins, NLRP3, and DNA methylation." (PMID 38515835, 2024).
silicosis (continued). "Among them, IL-1β, IL-6, TNF-α, and TGF-β1 have been identified as key pro-inflammatory and pro-fibrotic cytokines in silicosis." (PMID 39060930, 2024). "To investigate the possible role of S100A4 in silicosis, we first detected the secretion of S100A4, inflammatory indicator IL-6 and TNF-α, and fibrotic cytokine TGF-β1 and CTGF in the serum of patients with silicosis." (PMID 35379204, 2022). "Western blot showed that the expression levels of IL-1β, IL-6, TNF-α and TGF-β1 in lung tissue from the silicosis group were significantly elevated." (PMID 35959439, 2022). "AKEX0011 also significantly decreased the production of inflammatory factors such as TNF-α, IL-1β, IL-6, and TGF-β and the production of fibrosis markers such as collagen I, fibronectin, and α-SMA in silicosis." (PMID 35401236, 2022). "Results reflected those from the Western blot and tissue immunofluorescence staining; TLR4 and TNF-α were strongly expressed in the silicosis model group, and with the treatment of thalidomide, the expression levels of TLR4 and TNF-α were decreased." (PMID 35628464, 2022). "The secretion of TNF-α, IL-1β, IL-6, TGF-β1, and ox-LDL was significantly higher in the silicosis group than that in the HC group (p < 0.05)." (PMID 32351319, 2020). "The secretion of TNF-α, IL-6, TGF-β1, and ox-LDL was increased in patients with silicosis in comparison to controls, except for IL-1β." (PMID 32351319, 2020). "This suggests a milieu distinct from that described in silicosis, in which IL6 and TNF-α levels are typically increased." (PMID 31632407, 2019). "TNF-α deficient mice are resistant to developing fibrosis from silica and murine lung transfected with TNF-α resulted in spontaneous alveolitis, alveolar disruption, and a progressive fibrotic reaction, suggesting that TNF-α may play an important role in silicosis." (PMID 30643011, 2019). "Several potential biomarkers of human silicosis identified in human exposure studies, TGF-β, TNF-α and LDH, were also elevated in the BALF of silica-exposed DO mice." (PMID 29755467, 2018). "A previous study analyzing the plasma levels of TNF-α and MMP-9 in patients with silicosis has suggested that both molecules have higher expression in the early course of silica exposure." (PMID 29126438, 2017). "Next, the levels of the cytokines MCP-1, TNF-α and TGF-β, which have been established to play important roles in silicosis, were measured in macrophage supernatants." (PMID 27782836, 2016). "Numerous studies have been performed by scientists related to ROS, RNS, tumor necrosis factor (TNF), nuclear transcription factor-kβ (NF-kβ) and oxidative stress in apoptosis, but fewer studies was carried out for caspases in silicosis." (PMID 21120077, 2010). "Network pharmacology identifies TNF, MMP9, and NF-κB1 as key genes in PFD’s anti-silicosis effect." (PMID 40470053, 2025). "We found that PFD may alleviate inflammation and fibrosis in silicosis by inhibiting the TLR2/NF-κB pathway in epithelial cells, thereby reducing the production of TNF and MMP9." (PMID 40470053, 2025). "RT‒PCR showed that inflammatory cytokines (IL-1β, IL-6 and TNF-α) were upregulated in AMs, but IL-10 expression was not significantly different, which indicated that AMs in the early stage of silicosis were mainly inflammatory macrophages." (PMID 38454505, 2024). "Coincident with earlier findings, BIC suppressed TGF-β1 expression in BALF, serum, and lung tissues in our silicosis rat model, while the three other cytokines examined (IL-1β, IL-6, and TNF-α) were only decreased in BALF and lung tissue and not in serum." (PMID 39060930, 2024). "We only observed a significant and progressive increase in TNF-α levels in the HC→SS→PMF groups, suggesting that this factor could play an important role in the development of silicosis." (PMID 36675056, 2023). "Studies found that TNF-α and IL-6 were increased in the serum and BALF of patients with silicosis." (PMID 35379204, 2022).